EGFR (epidermal growth factor receptor)
Diseases named in the same sentence as EGFR in open-access papers (continued):
Sharing a sentence is not in itself a finding about the gene and the disease.
breast carcinoma (continued). "Breast cancer is pathologically demarcated by a plethora of abnormal gene profiles and transcripts that drive tumor initiation (MYC, Erb-B2 Receptor tyrosine kinase 2 (ERBB2), tumor progression (FOS, JUNB), proliferation and metastasis (epidermal growth factor receptor (EGRF))." (PMID 34299315, 2021). "In addition, unlike breast cancer, several aberrations are able to drive trastuzumab resistance in GC, including mutations in EGFR, MET, KRAS, PI3K, and PTEN genes, as well as EGFR, MET, and KRAS amplifications." (PMID 33916206, 2021). "Similarly, kindlin-2 interacts with EGFR and mediates EGF-induced breast cancer cell migration." (PMID 34338144, 2021). "To first determine the significance of phosphorylation of EGFR at T654 on metastasis, we compared levels of pT654 EGFR between the two cell lines and saw a significant increase in pT654 EGFR levels in the 4T1 metastatic compared with the 67NR nonmetastatic breast cancer cells." (PMID 31597954, 2020). "There are indications that EGF stimulation may lead to EGFR-MET interactions in breast cancer cells but no such effects were observed upon HGF activation." (PMID 32316583, 2020). "Downregulation of SHIP2 sensitised cells to EGFR inhibitors and resulted in increased apoptosis upon treatment with the EGFR inhibitors PD153035 and AG1478, compared to control cells, demonstrating a possible therapeutic option for SHIP2 silencing in breast cancer." (PMID 33276499, 2020). "Interestingly, the mutated form of EGFR (Variant III), usually expressed in different GBM and breast cancers, did not appear to be expressed in either of the two GSC lines considered." (PMID 32182759, 2020). "In breast cancers, SOX2 is up-regulated by the transcription factor FOXO1 (Forkhead box protein O1), the long non-coding RNA SOX2OT (SOX2 overlapping transcript), and the EGFR/Stat3 signaling pathway in a paracrine manner involving tumor-associated macrophages." (PMID 33553286, 2020). "Based on previously published results and the confirmed interplay between EGFR and ERs, our goal for this study was to evaluate the impact that different matrix substrates have on morphological aspects of breast cancer cells, following EGFR inhibition in the presence and absence of 17β-estradiol." (PMID 33050027, 2020). "As tumour tissues express CCL20 at the mRNA level and EGFR/Ras signalling upregulates CCL20 expression, we next performed immunohistochemical analysis of CCL20 protein expression and ERK activation in serial sections of tumour samples from breast cancer, melanoma and HNSCC patients." (PMID 32601464, 2020). "Moreover, by enhancing the levels of EGFR, HB-EGF, JUN and, in particular, FOS family members, ΔNp63 can enable sustained activation of the pro-oncogenic gene program induced by SMADs and AP-1 in HER2+ and/or EGFR+ breast cancer cells." (PMID 32350443, 2020). "One study found that HER3-positivity was an independent predictor of poor disease-free survival in breast cancer after adjusting for breast cancer subtype and other potential confounders, whereas EGFR-positivity did not independently predict disease-free survival." (PMID 32080212, 2020). "Given that both of the MCF7-BP1 and T47D-BP1 had higher levels of EGFR, phospho-EGFR, and phospho-Erk, it was hypothesized that the long-term exposure to IGFBP-1 was sufficient for the development of tamoxifen resistance in breast cancer cells." (PMID 32435229, 2020). "Knockdown of ANO1 in MCF-7 or T47D breast cancer cells resulted in a reduced tyrosine phosphorylation of EGFR (the site is not reported) and of STAT3 transcription factor in response to EGF, whereas overexpression of ANO1 in T47D cells increased phosphorylation EGFR and STAT3." (PMID 33250781, 2020). "Moreover, KLF4 and EGFR protein expression are generally mutually exclusive in the breast cancer cell lines we examined, suggesting that a threshold level of endogenous KLF4 may suppress the expression of EGFR in breast cancer cells." (PMID 32552913, 2020).
breast carcinoma (continued). "It is plausible that the known alternative pathways for growth, such as the epidermal growth factor receptor and PI3K/AKT/mTOR pathways, are responsible for the association between poor prognoses and high parity in luminal B-like (HER2 negative) subtype breast cancers." (PMID 32923400, 2020). "Also EGFR/HER-2 inhibition by the dual inhibitor lapatinib resulted in enhanced radiosensitivity in cancer cells of various entities, such as bladder cancer, peripheral nerve sheath tumors, pancreatic or breast cancer." (PMID 32903756, 2020). "Oncogenic pathways such as IL-6/Stat3, EGFR, NOTCH and TGF-β1 are involved in breast cancer (BC) cell mesenchymal phenotype and stemness." (PMID 32894152, 2020). "Moreover, in breast cancer MCF-7 and MDA-MB-231 cells, quercetin treatment inhibited epithelial-mesenchymal transition determined by expression of markers such as vimentin, Snail, N-cadherin, Twist, Slug, MMP2, and MMP9, by suppressing EGFR/VEGFR2 signaling." (PMID 31100782, 2019). "For instance, it has been demonstrated that ligand-activated GPER triggers EGFR transactivation and subsequent transduction events such as the activation of MAPK and PI3K, gene transcription and biological responses like proliferation, migration and angiogenesis in breast cancer cells and CAFs." (PMID 31370872, 2019). "However, EGFR-TKI treatment for breast cancer has been evaluated in clinical trials, but the trials are currently underwhelming, and there is still no available clinical drug targeting EGFR to inhibit TNBC metastasis." (PMID 31214503, 2019). "However, rshHDAC3Y328/331 did not rescue the invasion ability of breast cancer cells, indicating that EGFR–c-Src-mediated HDAC3 phosphorylation is involved in the invasion of breast cancer cells." (PMID 31430896, 2019). "Aside from EGFR-c-Src, HDAC3 may be critically involved in the malignant behavior of breast cancer." (PMID 31430896, 2019). "No involvement of MMP-17 in the EMT of HCC was found in the literature, but it was implicated in breast cancer progression, apparently by facilitating in vivo and in vitro breast cancer cell proliferation through outside-in EGFR signaling, but without acting as a protease." (PMID 31886121, 2019). "The primary role of EGFR activation in breast cancer cells is to stimulate exercise, and it has been demonstrated for the first time that maintaining the ability of EGFR cell surface expression through ACK1 can enhance the invasion ability of breast cancer cells." (PMID 31772931, 2019). "A combination of three proteins comprising the receptors EGFR, ERBB3/HER3, and the cyclin-dependent kinase inhibitor p27 (CDKN1B) was found to be a potential biomarker for dependence on PI3K/AKT vs. MAPK/ERK signaling for drug resistance in HER2 breast cancers." (PMID 35582587, 2019). "Furthermore, although previous studies have shown relevance between high PD-L1 expression and the presence of EGFR mutations in NSCLC33, we did not observe this association in breast cancer." (PMID 31591439, 2019). "Taken together, this suggests that ERBB2 requires EGFR or other members of the family possibly to dimerize for activation, such that down‐regulation of EGFR and potentially other members suppress the functionality of ERBB2, as has been previously reported in breast cancer." (PMID 30304546, 2019). "Human epidermal growth factor receptor 2 (HER2/ERBB2) is overexpressed in approximately 25% of breast cancers and drives hyperactivation of the HER2 pathway via downstream signaling initiated by receptor homo- or hetero-dimerization with other HER family members (HER2/HER2, HER2/EGFR, HER2/HER3)." (PMID 31796073, 2019). "b Common breast cancer subtype-marker expression in representative Her-2 positive (Her-2+), luminal A (ER/PR+, Her-2-, EGFR-, Ki-67% < 14%), luminal B (ER/PR+, Her-2-, EGFR-, Ki-67% ≥ 15%), and BLBC (ER-, Her-2-, EGFR+, CK5/6+) tissues by IHC (Red scale bar = 200 μm; Purple scale bar = 40 μm)." (PMID 31462314, 2019).
breast carcinoma (continued). "In vitro studies in HER2-amplified breast cancer cell lines and EGFR mutant NSCLC cell lines have demonstrated the strong anti-proliferative activity of dacomitinib, providing a rational for its progression into clinical testing against HER2 positive and EGFR mutant cancers." (PMID 30975211, 2019). "Interestingly, breast cancer cells co-expressing RANK and EGFR exhibited a significant enhancement of the EGFR downstream signaling and a higher invasive potential, supporting a synergistic effect of RANK and EGFR at both molecular and cellular level." (PMID 30621730, 2019). "Similarly, our results showed that the CD44+/CD24–/low BCSCs from HER2-negative breast cancer cells were associated with HER2 and EGFR overexpression and the radioresistant phenotype." (PMID 29464036, 2018). "Moreover, in cancer development, their functional crosstalk has been reported with EGFR activating MET or, conversely, with MET expression regulating EGFR tyrosine phosphorylation and cell growth, e.g., in the presence of gefitinib (EGFR inhibitor) in SUM229 breast cancer cells." (PMID 30227653, 2018). "The main objective of this study was to assess the interactions that occur between HER-2/EGFR and dual inhibitors (acting on both HER-2 and EGFR) and, consequently, understand their inhibition mechanisms and propose new models of drugs to treat related diseases, such as breast cancer." (PMID 30477154, 2018). "Recently, harmine was found to synergize with the anthracycline doxorubicin in the breast cancer cell line MCF-7 and harmine-mediated inhibition of DYRK1A destabilized epidermal growth factor receptor (EGFR) in aggressive glioblastomas and reduced EGFR-dependent glioblastoma growth." (PMID 29977157, 2018). "Besides, EGFR and HER2 were regulated by TFAP2C in breast cancer." (PMID 30124166, 2018). "In addition, a recent study reported that EGFR protein overexpression is a poor prognostic marker, as well as a negative predictive factor for trastuzumab treatment, in patients with HER2-positive primary breast cancer." (PMID 30521571, 2018). "Moreover, the upregulation of PTPIP51/PTP1B interaction upon EGFR inhibition is accompanied by an increase in the sensitivity of SK-BR3 cells (Her2 amplified breast cancer cell line) to the treatment, which is not seen after short term application." (PMID 30360441, 2018). "Consequently, TGF‐β failed to upregulate the mRNA and protein expression of EGFR in Sp1‐silenced breast cancer cells." (PMID 29215776, 2018). "Interestingly, we note that the knockdown of Akt1 did not induce the upregulation of EGFR mRNA expression in breast cancer cells, suggesting that the upregulation of EGFR is a transcription independent regulation." (PMID 30445978, 2018). "In accord with these results, breast cancer gene array profiling indicated that elevated expression of KLF4 in both MCF10A and MCF7 breast cancer cell lines upregulates transcription of several oncogenes and cell cycle activators such as MAPK, EGF/EGFR, IGF1, CYCLIN D2, CDK1, and CYCLIN E1." (PMID 30613353, 2018). "However, in the present analysis, co-module #5 showed that HER2-amplified and overexpressed breast cancers were sensitive to HER2 inhibition but were not sensitive to EGFR inhibition." (PMID 29950679, 2018). "Previous clinical studies revealed the significant efficacy of cancer therapies targeting EGFR in overall survival (OS), progression-free survival (PFS) and overall response (OR) in several types of cancers, including NSCLC, CRC, pancreatic cancer, breast cancer and SCCHN." (PMID 30404198, 2018). "While resistance mechanisms have been reported for anti-EGFR/HER2 therapies in HER2-overexpressing breast cancer and other cancers, the reason for the lack of efficacy of EGFR and EGFR/HER2 inhibitors in TNBC remains unknown." (PMID 29285221, 2017).
breast carcinoma (continued). "In order to choose cancer cell lines that expressed high levels of both c-MET and EGFR, Western blot and real time polymerase chain reaction (PCR) analyses were performed using four cell lines: ovarian carcinomas SKOV3 and A2780, renal carcinoma A498, and breast carcinoma MCF7." (PMID 29291022, 2017). "In addition, we identified c-METΔE14, HER2Y777L, EGFR-KDD, and HER4N855K as the most predominant driver mutants in these four tumors, indicative of the convergent central role of receptor tyrosine kinases in both lung and breast cancer." (PMID 29018192, 2017). "Mo-IPQA at a concentration of 10 μM was effective for up to 48 h after addition and completely abolished the phosphorylation of EGFR in EGF-stimulated HCC1954 breast cancer cells, whereas its effect was limited at a concentration of 20 μM in the MDA-MB-231 breast cancer cell line." (PMID 28166195, 2017). "Growth factor receptors, such as epidermal growth factor receptor 1 (EGFR), human epidermal growth factor receptor 2 (HER2), and insulin-like growth factor 1 receptor (IGF1R), are key regulatory nodes of the GFRN and are often aberrantly activated across breast cancer subtypes." (PMID 28446242, 2017). "However, the TMEM16A-associated proteins in HEK293 cells do not include EGFR, which forms a complex with TMEM16A and mediates TMEM16A-induced proliferation in breast cancer and HNSCC cells." (PMID 28893247, 2017). "Here, we take a systems biology approach to understand the molecular mechanisms that prevent breast cancer (BC) cells from responding to lapatinib, a dual kinase inhibitor that targets human epidermal growth factor receptor 2 (HER2) and epidermal growth factor receptor (EGFR)." (PMID 28481952, 2017). "Furthermore, analysis of published clinical data sets (GSE21653) revealed negative correlations of mRNA levels between ZNF516 and EGFR in different subtypes of breast cancers." (PMID 28947780, 2017). "Overexpression of EGFR and IGF-IR, lack of hormonal targeted cancer therapy, low survival rate and poor patient prognosis are hallmark features of the estrogen receptor alpha-negative (ERα-) breast cancer subtype." (PMID 27213582, 2017). "Additional studies reporting on steady expression levels of EGFR in breast cancer patient-derived CTCs, as well as an eradication of EGFR-positive and -negative CTCs following gefitinib treatment, further support the concept of antigen-specific targeting of CTCs." (PMID 27683128, 2017). "Breast cancer can be classified into different subtypes based on immunohistochemical expression of estrogen receptor (ER), progesterone receptor (PR), human epidermal growth factor receptor 2 (HER2), cytokeratins (CK5 or CK5/6), and epidermal growth factor receptor (EGFR)." (PMID 28545469, 2017). "Examples include trastuzumab (anti-HER2/neu) in combination with paclitaxel in breast cancer, rituximab (anti-CD20) in combination with cyclophosphamide/doxorubicin/vincristine/dexamethasone in non-Hodgkin's lymphoma or cetuximab (anti-EGFR) in combination with irinotecan in colon cancer." (PMID 27636991, 2016). "However, in breast cancer, prostate cancer, pancreatic cancer, gastric cancer, as well as in NSCLC cell lines, miR-146a-5p acted as a tumor suppressor through the targeting of Rac1/ROCK1/EGFR." (PMID 27494902, 2016). "Additionally, the increased tumorigenicity observed in response to AGK-mediated downregulation of FOXO1 in breast cancer may be due to aberrant activation of AKT, which is a major downstream effector of the EGFR." (PMID 26443540, 2016). "Although previous studies have revealed many potential biomarkers associated with poor prognosis in basal-like breast cancer, including basal cytokeratins (CK5/6, CK14, CK17), epidermal growth factor receptor (EGFR), c-kit, P63, P-cadherin and FOXC1, currently, there are no targeted treatments." (PMID 27322681, 2016).
breast carcinoma (continued). "Indeed, the cross talk between ER pathways and growth factor receptor pathways (EGFR, IGF-1, and HER2) has been involved in cell proliferation, survival, and resistance to endocrine therapy (TAM) in breast cancer (Yager & Davidson 2006, Pietras & Marquez-Garban 2007, Chang 2011)." (PMID 27357940, 2016). "In addition, miR-133a targeting of EGFR, miR-200c and miR-30c targeting of KRAS, miR-148b targeting of NRAS, miR-7 targeting of RAF1, miR-206 targeting of RASA1 and miR-21 targeting of SPRED1 have been reported in breast cancer cells." (PMID 27462780, 2016). "However, it was disappointing that breast cancer patients did not respond well to EGFR inhibitors alone." (PMID 27590506, 2016). "Thus, there may be a potential synergistic effect with E1A and EGFR-TKI combinational therapy by blocking the crosstalk between EGFR and other TKs in treatment of breast cancer." (PMID 27590506, 2016). "The potential dichotomy in PMCA2 levels between subtypes and its correlation with survival in the basal subtype is exemplified by the very different association between EGFR and PMCA2 in all breast cancers (positive correlation) versus the basal subtype (negative correlation)." (PMID 27148852, 2016). "Collectively these findings together with our studies suggest that integrin β1-ILK signaling pathway is required for feedback activation of AKT and can function as an alternative pathway, independent of EGFR in metastatic breast cancer cells to stimulate motility following MEK suppression." (PMID 27563827, 2016). "Thus, the expression of EGFR and HER-2 in these neoplasms may contribute to a better understanding of the progression mechanisms in malignant mammary tumors." (PMID 27490467, 2016). "EGFR-targeted clinical trials have not yielded convincing outcomes for breast cancer." (PMID 26025929, 2015). "Another possible reason for an EGFR IHC negative tumour responding to the treatment response may be heterogeneous overexpression of EGFR in such cases similar to apparently HER2 negative breast cancer cases showing response to Herceptin treatment." (PMID 26149458, 2015). "In summary, our findings represent a proof of principle by demonstrating the ability of a small molecule to selectively downregulate HER3 but not other epidermal growth factor receptor (EGFR) family members and inhibit downstream signaling in breast cancer cells and tumors." (PMID 25849870, 2015). "MCF-7, a breast cancer cell line that expresses low levels of EGFR, served as a negative control." (PMID 25918252, 2015). "GPER was first demonstrated to be responsible for estrogen’s activation of the MAP kinases ERK1/2 in ERα-and ERβ-negative breast cancer cells, through a mechanism involving the transactivation of epidermal growth factor receptor (EGFR) by metalloproteinase-released HB-EGF." (PMID 26470790, 2015). "Given the proto-oncogene status assigned to EGFR, it is not yet clear what role hypermethylation of EGFR might play in breast cancer progression." (PMID 26510686, 2015). "Given the promising negative impact of RBF3 on the viability of HER2 and EGFR overexpressing breast cancer cell lines, we examined whether RBF3 had activity against xenografts of human breast cancer." (PMID 25865227, 2015). "Therefore, the combination of an effective inhibitor for EGFR and HER2 with fulvestrant and dasatinib may further benefit patients with high ErbB family activity, endocrine therapy-resistance breast cancer." (PMID 24979294, 2014).